TDO2 (tryptophan 2,3-dioxygenase)
Diseases named in the same sentence as TDO2 in open-access papers (continued):
Sharing a sentence is not in itself a finding about the gene and the disease.
viral infection (2 papers, 2020 to 2021). "Our data shows that Tdo2-deficiency is highly compensated during viral infection, resulting in maintenance of the infection-associated reduction of the systemic tryptophan to kynurenine ratio." (PMID 33045014, 2020). "Specifically, viral infection repressed most tryptophan metabolism-associated genes in the liver up to 8 days after infection, but specifically induced Tdo2." (PMID 33045014, 2020). "Upon viral infection, Tdo2-deficient mice retained significantly elevated serum tryptophan levels, which was accompanied by an unexpected drastic increase of serum kynurenine." (PMID 33045014, 2020). "IFN-I specifically rewired tryptophan metabolism and induced hepatic tryptophan oxidation to kynurenine via Tdo2, correlating with altered concentrations of serum metabolites upon viral infection." (PMID 33045014, 2020). "Together, these data suggest that the observed systemic increase of kynurenine during homeostasis and upon viral infection of Tdo2-deficient animals is unlikely to be due to altered hepatocyte-intrinsic activity of IDO1 or IDO2." (PMID 33045014, 2020). "Tdo2-deficient animals did not display altered IFN-I responses in our viral infection model, which would argue against a direct regulatory feedback loop between IFN-I signaling and tryptophan-derived metabolites that was previously proposed in other model systems." (PMID 33045014, 2020). "Thus, the observed compensation of Tdo2-deficiency with respect to the serum tryptophan to kynurenine ratio upon viral infection might be independent of the IDO-axis." (PMID 33045014, 2020). "This suggests that exogenous viral infection in tumor (e.g., EBV, HPV, and HCV) is associated with the over-expression of IDO-1 and sometimes IDO-2 but not TDO-2." (PMID 34367262, 2021). "Downstream genes of Tdo2, including Kmo, Kynu, Maoa and Maob were either not found to be differentially expressed or downregulated by IFN-I signaling in hepatocytes or viral infection of the liver." (PMID 33045014, 2020).
atherosclerosis (1 paper, 2019). A disease characterized by the build-up of fatty material and calcium deposition in the arterial wall resulting in partial or complete occlusion of the arterial lumen. "Here, the expression patterns and activities of IDO1 and its isoenzyme tryptophan 2,3-dioxygenase (TDO) in aortas and blood samples of patients with atherosclerosis were investigated." (PMID 31637003, 2019).
cognitive deficits (1 paper, 2013). "Leptin, like melatonin, is a wide immune regulator, increasing natural killer cell activity and Th1 responses, while inhibiting the cAMP induction of tryptophan 2,3-dioxygenase (TDO) in astrocytes, thereby inhibiting cognitive deficits mediated by TDO induction of kynurenic acid." (PMID 23497361, 2013).
colon adenocarcinoma (1 paper, 2020). "TDO2 mRNA expression was significantly higher in SK-Mel-28 cells, compared to the human colon adenocarcinoma cell line and to the human endothelium, being 4.8 ± 0.9 fold over HUVEC and 12.5 ± 5 over HCT-8." (PMID 32776284, 2020).
Delusion (1 paper, 2021). A delusion is a fixed false belief held despite evidence to the contrary. "Furthermore, six autoantibodies were associated with specific psychopathology symptoms: anti-AP3B2 (persecutory delusions), anti-TDO2 (hallucinations), anti-CRYGN (initial insomnia); anti-APMAP (poor appetite), anti-OLFM1 (above-median cognitive function), and anti-WHAMMP3 (anhedonia and dysphoria)." (PMID 34518517, 2021).
endometrial cancer (1 paper, 2021). Primary or metastatic malignant neoplasm involving the endometrium (mucous membrane that lines the endometrial cavity). "ERV3-2 expression was correlated with all three genes in ER− HER2− and HER2+ breast, colon, and endometrial cancers; and IDO-1 and IDO-2 (but not TDO-2) in ER+ HER2− breast, gastric, lung, prostate, cervical, and head-neck squamous cell cancers." (PMID 34367262, 2021).
endometriosis (1 paper, 2023). The growth of functional endometrial tissue in anatomic sites outside the uterine body. "Moreover, positive expression of IDO1, TDO2 and IL4I1 was related to advanced stage, metastasis, bilateral tumours, endometriosis and tumour rupture (p < 0.05) respectively." (PMID 38062922, 2023).
endotoxemia (1 paper, 2020). "Previous studies highlighted a potential beneficial role of Tdo2 in endotoxemia, while certain tumors upregulate Tdo2 to repress tumor-specific T cell responses." (PMID 33045014, 2020).
epileptic seizures (1 paper, 2024). "In contrast, Dsp knockdown increased the expression of the mature neuronal markers Calb1, Tdo2, and Ntf3, which are negatively regulated by strong neuronal activation, such as in the ECS and epileptic seizures." (PMID 39176381, 2024).
Fulminant hepatic failure (1 paper, 2020). Hepatic failure refers to the inability of the liver to perform its normal synthetic and metabolic functions, which can result in coagulopathy and alteration in the mental status of a previously healthy individual. "In vivo transdifferentiation of hBMSCs in pigs with fulminant hepatic failure confirmed the similarly upregulated expression of 5 hepatogenic genes (TDO2, HP, SERPINA3, LBP and SAA1), showing a 150-fold change in liver tissues at 7 days after hBMSC transplantation." (PMID 32038110, 2020). "Finally, the five genes (TDO2, HP, SERPINA3, LBP and SAA1) validated in hBMSC transplantation with a fulminant hepatic failure (FHF) model in pigs could be potential biomarkers for the characterization of hBMSC-HLCs." (PMID 32038110, 2020).
Hepatic steatosis (1 paper, 2024). Steatosis is a term used to denote lipid accumulation within hepatocytes. "Collectively, these findings suggest that TDO2 upregulation is associated with hepatic steatosis, supporting its potential role as a biomarker or therapeutic target in the context of MASLD." (PMID 39364706, 2024). "Thus, loss of hepatic Tdo2 alleviated hepatic steatosis in HFD‐fed rats." (PMID 39364706, 2024). "In our study, we discovered YY1 promoted transcription of TDO2 by activating H3K27ac modification in its gene region, thereby exacerbating the progression of hepatic steatosis." (PMID 39364706, 2024).
ischemia (1 paper, 2022). A hypoperfusion of the BLOOD through an organ or tissue caused by a PATHOLOGIC CONSTRICTION or obstruction of its BLOOD VESSELS, or an absence of BLOOD CIRCULATION. "Although we did not observe consistent changes in the protein levels of Tdo2 throughout hepatic IR process, dramatic upregulation of Afmid at both mRNA and protein levels was evident from the ischemia stage." (PMID 36310151, 2022).
mesenchymal tumors (1 paper, 2017). "All three GABA related genes -- glutamate decarboxylase 1 (GAD1) and 2 (GAD2) and 4-aminobutyrate aminotransferase (ABAT) -- were lower in mesenchymal tumors, which in contrast showed higher IDO1 (indoleamine 2, 3-dioxygenase 1) and TDO2 (tryptophan 2, 3-diaxygenase)." (PMID 28245795, 2017).
microphthalmia (1 paper, 2023). Congenital or developmental anomaly in which the eyeballs are abnormally small. "A similar search of DR17 using the term microphthalmia resulted in 22 genes significant for the small eyes phenotype: Aldh1a3, Aff4, Bmp4, Cdk4, Cox6b1, Cxcr4, Dync1li1, Eef1d, Fgd1, Gne, Grh12, Mab21l2, Maf, Med13l, Mllt10, Mthfd2, Pex6, Phgdh, Ssr1, Stim1, Tdo2, and Vps26c." (PMID 36737727, 2023).
oropharyngeal squamous cell carcinoma (1 paper, 2024). "In summary, through bioinformatics analysis and immunohistochemistry, we hypothesize the involvement of HIF-1a in regulating TDO2 gene expression and downstream glycolytic pathways in HPV-positive oropharyngeal squamous cell carcinoma." (PMID 38887298, 2024).
osteoarthritis (1 paper, 2025). A noninflammatory degenerative joint disease occurring chiefly in older persons, characterized by degeneration of the articular cartilage, hypertrophy of bone at the margins and changes in the synovial membrane. "Interestingly, expression of TDO2, a key enzyme of the kynurenine pathway, in synovial fluid is a marker of osteoarthritis incidence and severity." (PMID 41256619, 2025).
ovarian serous cystadenocarcinoma (1 paper, 2023). A malignant serous cystic epithelial neoplasm arising from the ovary. "According to an analysis of gene expression data from The Cancer Genome Atlas and Genotype‐Tissue Expression project, the mRNA level of TDO2 is upregulated in ovarian serous cystadenocarcinoma in comparison to normal tissue, and higher TDO2 expression resulted in cancer progression." (PMID 38062922, 2023).
ovarian tumor (1 paper, 2024). "In line with this, we found that IDO1 inhibition alone (epacadostat), TDO2 inhibition alone (680c91), and dual TDO2/IDO1 inhibition (AT-0174) all reduced PD-L1 expression on ovarian tumor cells." (PMID 38451784, 2024).
peritoneal cancers (1 paper, 2023). A peritoneum cancer that is located in the inside of the abdomen. "Tryptophan metabolites generated by indoleamine-2,3-dioxygenase (IDO) and tryptophan-2,3-dioxygenase (TDO) have been shown to promote tumor growth and immune evasion in peritoneal cancers." (PMID 37233659, 2023).
viral hepatitis (1 paper, 2020). An acute or chronic inflammation of the liver parenchyma caused by viruses. "To test whether TDO2 affects pathophysiology in a model of viral hepatitis, we infected Tdo2-deficient mice and littermate wild type controls (Tdo2–/–and WT) with 2x106 focus forming units (FFU) of LCMV Cl13." (PMID 33045014, 2020).
tumor (148 papers, 2014 to 2026). "This process is catalyzed by key enzymes, including indoleamine 2,3-dioxygenase 1 (IDO1) and tryptophan 2,3-dioxygenase 2 (TDO2) and the levels of these metabolites are closely associated with the malignant features of the tumour (Refs 6, 7)." (PMID 40040508, 2025). "The orally available dual IDO1/TDO2 inhibitor, AT-0174, significantly inhibited tumor progression, reduced tumor-associated macrophages, and reduced expression of immune-suppressive proteins on immune and tumor cells." (PMID 38451784, 2024). "Tryptophan 2,3-dioxygenase (TDO) encoded by TDO2, a rate-limiting enzyme in the kynurenine pathway, catabolizes tryptophan to kynurenine, evades immune surveillance, and promotes tumor growth." (PMID 36118672, 2022). "Most of these genes were reported to be associated with tumor metastasis, such as TDO2, CYTL1, and LDB2." (PMID 35982908, 2022). "TDO2 overexpression was significantly associated with T classification, N classification, and M classification, tumor stage, recurrence, and basal type, and with the expression of CD44 and aldehyde dehydrogenase 1 (ALDH1) in BC." (PMID 34101386, 2021). "Researchers have reported that an overexpression of the tryptophan catabolizing enzymes indoleamine 2,3-dioxygenase 1/2 or tryptophan 2,3-dioxygenase are associated with tumour progression." (PMID 33648471, 2021). "Expression of tryptophan 2,3‐dioxygenase (TDO2) is associated with tumor progression and worse survival in some other cancers." (PMID 34101386, 2021). "We previously reported that the expression of TDO2 was linked with tumor progression and poor prognosis and cancer stem cells (CSCs) in esophagus squamous cell carcinoma." (PMID 34101386, 2021). "Overexpression of TDO2 enhanced tumor cell survival and associated with worse outcomes in patients with these tumors." (PMID 34101386, 2021). "IDO-1 and TDO-2 induction in tumors are crucial mechanisms implicated to play pivotal roles in suppressing anti-tumor immunity." (PMID 25415278, 2014). "Mutation and DNA methylation in tumor cells may play a role in TDO2's involvement in tumor development." (PMID 36118672, 2022). "For example, 19DD, a HIST + DD sample, harbored an 8.1-fold copy-number amplification in the chr4 region, including TDO2, which encodes a tryptophan 2,3-dioxygenase that converts tryptophan to kynurenine, a metabolite known to be involved in tumor growth and poor prognosis." (PMID 34206586, 2021). "For example, miR‐126‐5p overexpression enhances TDO2 expression, promoting tumor proliferation and metastasis." (PMID 41332472, 2025). "TDO2, as one of the key enzymes in the Kyn pathway, was found to be highly expressed in the tumour tissues of PCs." (PMID 40525887, 2025). "Single-cell transcriptomics has revealed heterogeneity in IDO1/TDO2 expression across tumor and stromal compartments, demonstrating that localized tryptophan metabolism can differentially shape immune niches within the same tumor." (PMID 41562065, 2025). "Our aim was to explore the correlation between key KP markers; IDO1, IDO2, TDO2, its primary effector target aryl hydrocarbon receptor (AhR) and a comprehensive set of clinical- and tumour characteristics." (PMID 40471422, 2025). "M4112, as an effective and selective dual inhibitor of IDO1 and TDO2, was shown in a tumor mouse model to possess dual inhibitory effects." (PMID 39940736, 2025). "High expression of TDO2 in HCC tissues promotes tumor cell migration and invasion through the Wnt5a signaling pathway." (PMID 41332472, 2025). "Functioning as a potent miR-4738-3p sponge in HCC, CircZNF566 alleviates the inhibitory impact of miR-4738-3p on TDO2, thereby enhancing TDO2 expression in tumor cells and fostering the progression and metastasis of HCC." (PMID 40136551, 2025).
tumor (continued). "According to the single-cell transcriptomic landscape of precancerous and cancerous tissues in oral carcinogenesis, a subset of myofibroblasts expressing TDO2 was found, located distantly from the tumor nests, with CD4 and CD8 T cells enriched around them." (PMID 40136551, 2025). "Our aim is to investigate the KP with a broadened scope, exploring the IDO1, IDO2, TDO2 and AhR interplay with both clinical as well as tumour characteristics." (PMID 40471422, 2025). "IDO1 and TDO2, essential enzymes in the Kyn metabolic pathway, are commonly overexpressed in numerous tumor types, including those affecting the pancreas, breast, and brain." (PMID 41332472, 2025). "In KPIC orthotopic PC mice, inhibition of the IDO1/TDO2-Kyn-AhR pathway resulted in delayed tumor growth, suppressed tumor metastasis, and enhanced tumor cell apoptosis." (PMID 40136551, 2025). "Elevated expression of tryptophan-2,3-dioxygenase 2 (TDO2) and indoleamine 2,3-dioxygenase 1 (IDO1) enhances kynurenine (Kyn) production, which fosters PCa progression through tumor-associated immunosuppression and direct pro-survival signaling." (PMID 41179661, 2025). "Activation of AhR by KYN, a product of IDO1 and TDO2, prompts the generation of immune-tolerant dendritic cells (DCs) and regulatory T cells, which together shape a tumor immune microenvironment incapable of recognizing and destroying cancer cells." (PMID 38887298, 2024). "Sodium Tanshinone IIA Sulfonate (STS) inhibits both IDO1 and TDO2, restraining tumor growth and enhancing the anti-tumor activity of PD1 antibodies." (PMID 38462620, 2024). "TDO2 overexpression correlates closely with HCC tumor size, degree of differentiation, and M phase, with higher TDO2 levels associated with worse overall survival and disease-free survival (DFS)." (PMID 38462620, 2024). "The expression of IDO1, TDO2, and other enzymes in the kynurenine pathway varies widely among different tumor types and even among patients with the same type of cancer." (PMID 39911818, 2024). "Direct inhibition of IDO1 and TDO2 is an alternate strategy to decrease kynurenine production and target tumor immune evasion." (PMID 38339226, 2024). "Tryptophan metabolism through indoleamine 2,3-dioxygenase (IDO) and tryptophan 2,3-dioxygenase (TDO), which are involved in the kynurenine pathway, is postulated to be a leading cause of tumor immune escape." (PMID 37545500, 2023). "IDO1- and TDO2- mediated degradation of tryptophan by cancer cells is a driver of immune suppression in the tumor microenvironment through recruitment and activation of myeloid-derived suppressor cells (MDSCs) and induction of anergy of CD8+ T cells." (PMID 36900311, 2023). "Like IDO1, TDO2-mediated Kyn promotes tumor immune suppression through AhR-signaling in various cancer types." (PMID 37876966, 2023). "We also report early in vivo data in support of the potential therapeutic efficacy of the dual IDO1/TDO2 inhibitor AT-0174 as a part of immuno-therapeutic treatment that disrupts tumor metabolism and enhances anti-tumor immunity." (PMID 37226257, 2023). "Indoleamine-2,3-dioxygenase (IDO) as well as tryptophan-2,3-dioxygenase (TDO) are important in tumoral cells defense against immunity response." (PMID 37218976, 2023). "Subsequently we confirmed both in vivo and in vitro experiments that TDO2 and miR-126-5p mimics can promote the proliferation, invasion and migration of HCC cells, while knockdown TDO2 and miR-126-5p inhibitors can inhibit the tumor progression of HCC cells." (PMID 35056756, 2022). "Recently, Cheong and Sun described the switch of DCs toward an immunotolerant phenotype consequent to the activation of (IDO-1) and tryptophan 2,3-dioxygenase 2 (TDO2) in the tumor microenvironment." (PMID 35203299, 2022). "Considering the importance of IDO1 and TDO2 inhibitors in tumor immunotherapy, we developed an extracellular inhibitor screening model." (PMID 35571116, 2022).